INS (insulin)
Diseases named in the same sentence as INS in open-access papers (continued):
Sharing a sentence is not in itself a finding about the gene and the disease.
diabetes (continued). "The secretion and expression of apelin, which is secreted from the heart, blood vessels, and white adipose tissue, are regulated by insulin; thus, apelin is closely related to metabolic syndrome and other disorders caused by diabetes or insulin resistance." (PMID 30696454, 2019). "The topic words in the history of present illness section, we can observe glucose, diabetes, insulin, and hydrochlorothiazide, which are related to diabetes disease considered as a potential risk factor of cognitive decline." (PMID 31391041, 2019). "It is known that diabetes mellitus is characterized by a deficiency in insulin secretion and by a low response of the organs in the action of insulin." (PMID 31315213, 2019). "Diabetes mellitus (DM) is a metabolic disorder characterized by hyperglycemia caused by insufficient insulin secretion and/or insulin action." (PMID 30823412, 2019). "Different methylation of Stc1 was one of the genome sites influenced by maternal diabetes during pregnancy, which was associated with impaired insulin secretion and higher risk of T2DM." (PMID 31379744, 2019). "Of particular interest, diabetes mellitus is a prevalent metabolic disease that occurs as an outcome of deficient insulin secretion and/or action, and persists to be a leading global health problem." (PMID 31319588, 2019). "Insulin is a high-risk medication used in the treatment of both type 1 and type 2 diabetes mellitus." (PMID 30704103, 2019). "Although most national obstetrical associations continue to recommend insulin as first-line pharmacotherapy for diabetes in pregnancy given its inability to cross the placenta, certain oral glycaemic agents are gaining attention." (PMID 31119029, 2019). "Antipsychotics likely increase the risk of diabetes through weight gain and directly by adversely affecting insulin sensitivity and secretion." (PMID 31478094, 2019). "PGC‐1α is strongly induced in the livers of fasting mice and mice with insulin action deficiency, such as streptozotocin‐induced diabetes, ob/ob, and liver IR‐knockout mice." (PMID 31313501, 2019). "Intracerebroventricular administration of the pro-diabetes drug streptozotocin in rats results in cognitive impairment with deficits in spatial learning and memory, brain insulin resistance and deficiency, and AD-type neurodegeneration." (PMID 31126115, 2019). "The identification of mutations in the INS gene coding sequence increased our understanding how proinsulin misfolding contributes to the development of ß cell failure and diabetes." (PMID 31184304, 2019). "E2 protected pancreatic β cells from apoptosis and prevented insulin-deficient diabetes mellitus in mice." (PMID 30790128, 2019). "As is well-known, Asians have a higher risk of developing diabetes due to impaired insulin secretion which was induced by insufficient pancreatic β-cell mass or functional defects." (PMID 30873113, 2019). "In diabetes mellitus type 1, pancreatic beta cells are damaged by the immune system, therefore, patients must use exogenous insulin to control blood sugar and inhibit risk of developing long-term complications." (PMID 30834086, 2019). "In this study, we expanded the sample size, further investigated the association of PV with duration of diabetes, and explored the relationship between PV feature and loss of insulin secretory capacity in patients with various durations of type 2 diabetes." (PMID 31467928, 2019). "In fact, crosstalk between both mechanisms is related with alterations in glucose homeostasis and can lead to the diabetes-associated insulin-resistance status." (PMID 31487953, 2019). "Prolonged and intensive insulin therapy in elderly diabetes patients has been shown to increase the risk of hypoglycemia, which has a direct association with impaired cognitive function." (PMID 30344304, 2018).
diabetes (continued). "The potential benefits of combining GLP-1RAs with basal insulin are contemplated in the current position statement of both the American Diabetes Association (ADA) and the American Association of Clinical Endocrinologists (AACE)." (PMID 29636825, 2018). "This is one mechanism implicated in the pathogenesis of INS resistance in the setting of obesity or diabetes." (PMID 30116740, 2018). "In our study, performed in a tertiary care center, a low adherence to diabetes screening after a gestation complicated by GDM was observed and the only factor implicated with returning for diabetes screening was the use of insulin during pregnancy." (PMID 29308091, 2018). "Oxidative stress promotes insulin secretion defects, decreases insulin sensitivity in peripheral tissues, and causes other complications associated with diabetes, and oxidative stress control is helpful in diabetes treatment." (PMID 29870561, 2018). "Type 2 diabetes mellitus (T2DM) is characterized by a relative loss of functional beta-cell mass leading to insufficient insulin secretion during insulin resistance." (PMID 30557325, 2018). "Type I diabetes mellitus, which is caused by a deficiency in insulin secretion, accounts for 5–10% of people with diabetes." (PMID 30424007, 2018). "Subjects with GG genotype of rs2920502 in PPARγ, who had better early- and total-stage insulin secretion function and better serum lipid condition, had a decreased risk for diabetes." (PMID 29849618, 2018). "An educational program for insulin self-adjustment associated with structured self-monitoring of blood glucose significantly improves glycemic control in patients with type 2 diabetes mellitus after 12 weeks: a randomized, controlled pilot study." (PMID 29527102, 2018). "Diabetes mellitus is a metabolic disease that is caused by deficient insulin secretion or poor insulin utilization, with hyperglycaemia as the main symptom." (PMID 29587624, 2018). "Visits to endocrinologists and purchases of oral diabetes medication and insulin were associated with a higher risk of mortality (HRs (95% CIs) 1.20(1.07–1.35), 1.35(1.26–1.46) and 3.36(2.92–3.87) respectively)." (PMID 30540832, 2018). "When framing recommendations for diabetes and CV risk, following factors should be reviewed: hypertension, smoking, obesity, increased fasting insulin and IR, lifestyle intervention, and atherogenic lipid profile (abnormal cholesterol, high triglycerides)." (PMID 29527102, 2018). "The limitations of SC insulin therapy for prandial glucose control put individuals with insulin-treated diabetes at risk for both postprandial hyperglycemia and late postprandial hypoglycemia." (PMID 29707584, 2018). "Type 2 diabetes mellitus (T2DM) is characterized by chronic hyperglycemia caused by impaired insulin secretion and/or insulin resistance." (PMID 29636044, 2018). "The plausible explanation of the association between the longer duration of diabetes and the poor glycemic control is the exhaustion of the pancreas to produce more insulin." (PMID 29884216, 2018). "The many causes of endothelial dysfunction have been linked to key hallmarks of diabetes such as oxidative stress, insulin resistance, ROCK activation, and proinflammatory signaling of Wnt5a." (PMID 29928236, 2018). "In a representative population of women followed over 34 years, we investigated the prospective association between fasting serum insulin and dementia, taking into account the incidence of diabetes mellitus." (PMID 29997193, 2018). "A previous report has indicated that, in diabetes, protein synthesis is decreased in all tissues, which is due to the relative deficiency of insulin and to depressed synthesis of Hb." (PMID 29463309, 2018). "For example, being a crucial drug for treating diabetes, insulin is associated with the injection amyloidosis, found at the site of recurrent insulin injections." (PMID 30123793, 2018).
diabetes (continued). "Optimal sleep (7–8 h per night) has been shown to maintain metabolic health, aid in weight loss, and increase insulin sensitivity, while short duration (< 5–6 h) or longer duration (> 8–9 h) of sleep was associated with increased risk of diabetes." (PMID 29527102, 2018). "The factors associated with CAN progression were age, diabetes duration, use of insulin, and increased HbA1c levels between baseline and follow-up CARTs, which were similar to findings from previous studies." (PMID 30071872, 2018). "Having secondary education, previous diabetes education, a ‘diabetes confidant’, and insulin use were each associated with a higher DSMES Score." (PMID 30214472, 2018). "Metformin and/or basal insulin are recommended by the American Diabetes Association (ADA) 2018 guidelines and the International Society for Pediatric and Adolescent Diabetes when lifestyle modification alone is insufficient to improve glycemic control." (PMID 30014302, 2018). "Measuring insulin sensitivity is therefore of importance in identifying individuals at risk of developing diabetes and for the evaluation of diabetes-focused interventions." (PMID 29940866, 2018). "Increased skinfold thickness has also been associated with increased steady-state insulin depot size in persons with diabetes during continuous subcutaneous insulin infusion (CSII), likely as a result of delayed absorption." (PMID 30116732, 2018). "There was impairment of hexokinase enzyme (key enzyme in glycolysis) activity in diabetes mellitus probably due to deficiency of insulin." (PMID 29387371, 2018). "Deliberate insulin omission is a long recognized cause of recurrent diabetic ketoacidosis in adolescents with T1DM." (PMID 29744106, 2018). "Diabetes mellitus is a disease characterized by hyperglycemia caused by the impairment of insulin secretion, insulin action or both." (PMID 29636032, 2018). "Diabetes represents a group of metabolic disorders caused by impaired insulin signaling and function." (PMID 30364261, 2018). "Type 2 diabetes mellitus (T2DM) is a worldwide health problem caused by resistance to insulin action." (PMID 30360393, 2018). "Significant risk factors for CAUTI were age, diabetes requiring insulin therapy, low ADL score, and long hospitalization." (PMID 29093305, 2018). "Since weight gain in diabetes has been shown to adversely affect cardiovascular risk, this has to be considered as a drawback of combining insulin and glucagon for the treatment of diabetes." (PMID 29558502, 2018). "In diabetes, hypoglycaemia results from profound disturbances in glucose homeostasis and, in particular, the inability to ‘shut off’ exogenous insulin delivery and loss of normal physiological regulation of glucagon secretion." (PMID 29417183, 2018). "The achievement of target glycemic control at week 24 was also negatively associated with duration of diabetes in the Asian population, demonstrating the importance of timely initiation of basal insulin." (PMID 29524190, 2018). "Measuring insulin sensitivity is of importance in identifying individuals at risk of developing diabetes and to evaluate diabetes-focused interventions." (PMID 29940866, 2018). "Tamoxifen and coffee appear to be associated with diabetes and the insulin pathway, although in opposite directions." (PMID 29928262, 2018). "Diabetes is a group of metabolic diseases characterized by deficient insulin secretion and/or action which leads to hyperglycemia, and, in turn, to abnormal metabolism of carbohydrates, fats, and proteins in insulin target tissues." (PMID 30483218, 2018). "Insulin plays a central role in glucose homeostasis, and impairment of insulin action causes glucose intolerance and leads to type 2 diabetes mellitus (T2DM)." (PMID 29560274, 2018).
diabetes (continued). "Approximately 415 million people (about 8.3% of the world’s population) had diabetes worldwide in 2015, with 90% of the cases classified as Type 2 DM, which is caused by insulin resistance that arises mostly from being overweight and from a lack of exercise." (PMID 30373127, 2018). "For example, in a Mendelian randomisation study no causal links were found between IL-1 receptor antagonist (IL-1Ra) or C-reactive protein (CRP) and diabetes-related outcomes, while IL-1Ra is associated with 2 h glucose and insulin sensitivity." (PMID 29159468, 2018). "After controlling the confounding factors, longer duration of diabetes and engaging on insulin therapy were associated with poor glycemic control." (PMID 29505602, 2018). "Increased BCAA concentrations are found in various insulin-deficient and -resistant states, especially diabetes and obesity." (PMID 29755574, 2018). "Here we focus on islet amyloid polypeptide (IAPP) mediated loss-of-insulin secreting cells in patients with diabetes." (PMID 29615609, 2018). "Diabetes is a chronic degenerative disease, characterized by hyperglycaemia caused by defects in insulin activity, secretion, and/or metabolism, that has become an epidemic and is now one of the biggest health challenges." (PMID 29495516, 2018). "Human amylin is a 37-residue peptide hormone (hA1-37) secreted by β-cells of the pancreas and, along with insulin, is directly associated with type 2 diabetes mellitus (T2DM)." (PMID 30463298, 2018). "Diabetes is a metabolic disorder characterised by hyper-glycemia resulting from either deficient secretion of insulin or insulin action." (PMID 29746898, 2018). "The frequency of hypoglycaemia in type 2 diabetes is known to be associated with diabetes duration, and is markedly higher in individuals treated with insulin for a long period than in those in the initial stages of treatment." (PMID 28983693, 2018). "Type 1 diabetes mellitus (T1DM) is a pathology mediated by an autoimmune response that destroys the pancreatic β cells responsible for insulin production, resulting in a deficiency of this hormone." (PMID 29796316, 2018). "The development of diabetes has been associated with increased ER stress and apoptosis in pancreatic beta cells, leading to insufficient insulin secretion." (PMID 30584460, 2018). "A case study showed that autosomal dominant mutations within the NeuroD1 (BETA2) gene were causing a dysregulation in the expression of the insulin gene, leading to the development of diabetes before the age of 25." (PMID 29922517, 2018). "Lifestyle factors conferring increased diabetes risk are associated with elevated basal insulin levels (hyperinsulinaemia)." (PMID 30541568, 2018). "Type 1 diabetes mellitus (insulin-dependent) is related to insulin deficiency due to mechanisms that reduce serum concentration of this hormone." (PMID 30088548, 2018). "The pathogenesis in type 1 and the late phase of type 2 diabetes mellitus is associated with T-cell infiltration of the pancreatic islets (insulitis) and is characterized by a progressive T-cell-mediated destruction of the insulin-producing β-cells." (PMID 30345315, 2018). "As GH is a potent antagonist of insulin action, uncontrolled acromegaly is associated with insulin resistance, hyperglycemia, and eventually diabetes." (PMID 30232095, 2018). "Diabetes mellitus is a metabolic disease characterized by hyperglycemia which is caused by a deficiency of insulin or disorders of the insulin’s actions." (PMID 30140408, 2018). "Several studies have suggested that an increase in PCSK9 levels is associated with higher fasting insulin levels in general populations and patients with diabetes." (PMID 29618348, 2018). "Type 2 diabetes mellitus is a complex disease characterized by the improper use of insulin by the pancreatic beta cells associated with hyperglycemia and insulin resistance." (PMID 30246020, 2018).
diabetes (continued). "Maternal diabetes and obesity induce marked abnormalities in glucose homeostasis and insulin secretion in the fetus, and are linked to obesity, diabetes, and metabolic disease in the offspring." (PMID 30201937, 2018). "Diabetes mellitus refers to a metabolic disorder resulting in high blood glucose levels due to either reduced insulin levels caused by destruction of insulin-producing beta-cells (type 1 DM), or insulin resistance (type 2 DM)." (PMID 30360455, 2018). "Diabetes mellitus is a common medical disorder characterized by an absolute or relative deficiency of insulin, thereby causing a chronic state of hyperglycemia." (PMID 29898693, 2018). "To further probe the relationship between weight gain and diabetes susceptibility in aged mice fed a WD, we proceeded to examine in vivo glucose-stimulated insulin secretion." (PMID 30546031, 2018). "In the case of diabetes mellitus, insulin-insensitivity are reported to increase the risk of several cancers, while it reduces risks of other cancers." (PMID 29961900, 2018). "To discover roles of candidate diabetes risk genes in insulin regulation, we measured insulin output (total and circulating levels) after RNAi induced knockdown of T2D candidate risk factors, not known to be regulators of insulin production or secretion." (PMID 30242153, 2018). "The results of this analysis clearly show that patients on sulphonylurea with high HbA1c, eGFR below 50 ml/min/1.73 m2, and diabetes duration longer than 5 years are at very high risk to start insulin treatment during follow-up." (PMID 30327785, 2018). "The development of diabetes has been linked to the loss of self-tolerance to beta cell autoantigens leading to the Th1-mediated destruction of insulin-producing beta cells." (PMID 29541642, 2018). "STZ is used to destroy pancreatic β-cells and thereby induces insulin-deficient diabetes in animal models." (PMID 29599810, 2018). "American Association of Clinical Endocrinologists and American College of Endocrinology (AACE/ACE) and ADA/European Association for the Study of Diabetes (EASD) guidelines recommend initiating insulin therapy with basal insulin." (PMID 29527102, 2018). "Diabetes Mellitus (DM) is a clinical syndrome that is characterized by hyperglycemia, which is caused due to a deficiency of insulin, and affects all age groups." (PMID 29659479, 2018). "The American Diabetes Association (ADA)/European Association for the Study of Diabetes (EASD) issued guidelines recommending long-acting insulin for patients with HbA1C > 7.0% after treatment with two oral antidiabetic drugs (OADs)." (PMID 29476413, 2018). "Basal insulin is recommended as a convenient way to initiate insulin treatment by most international treatment guidelines, and by the Chinese Diabetes Association11–13." (PMID 29862021, 2018). "Women have greater peripheral fat deposition, which, in contrast to visceral fat, is associated with improved insulin sensitivity, and was protective for diabetes, as reported locally." (PMID 30260983, 2018). "Insulin doses were adjusted to achieve fasting and 2-h postprandial glucose targets according to American Diabetes Association guidelines." (PMID 29232162, 2018). "After controlling for factors in the multivariable regression model, secondary education, previous diabetes education, having a confidant for diabetes, and insulin intake remained statistically significant and associated with higher average DSMES Score." (PMID 30214472, 2018). "In contrast, being in the high insulin tertile was associated with high values of cardiovascular risk factors and with excess risk of diabetes mellitus." (PMID 29997193, 2018). "In the PREDICTIVE study, the frequency of hypoglycemia in insulin-treated patients showed a significant, positive association with duration of diabetes, and number of insulin injections but was inversely related to HbA1c." (PMID 29433560, 2018).